LRRFIP1 (LRR binding FLII interacting protein 1)
Diseases named in the same sentence as LRRFIP1 in open-access papers (continued):
Sharing a sentence is not in itself a finding about the gene and the disease.
Allergy (1 paper, 2025). An allergy is an immune response or reaction to substances that are usually not harmful. "Proteins such as LRRFIP1, involved in monocyte activation and lysosomal function, and PAG1, linked to allergy development, were prominently recognized." (PMID 41303346, 2025).
autoimmune disease (1 paper, 2019). A disorder resulting from loss of function or tissue destruction of an organ or multiple organs, arising from humoral or cellular immune responses of the individual to their own tissue constituents. "The decreased binding of LRRFIP1/GCF2 to TNF-α promotor is likely to cause over-expression of TNF-α and various autoimmune diseases, such as rheumatoid arthritis." (PMID 30709060, 2019). "Dysregulations of LRRFIP1/GCF2 play broad and critical roles in the development of human diseases such as infections and autoimmune diseases, neurological, cardiovascular, metabolic diseases and cancer." (PMID 30709060, 2019). "The variant TNF-α gene promotor, which is not bound nor repressed by LRRFIP1/GCF2 is discussed in relation to autoimmune diseases in Section 3.1." (PMID 30709060, 2019).
bipolar disorder (1 paper, 2024). A disorder of the brain that causes unusual shifts in mood, energy, activity levels and the ability to carry out day-to-day tasks. "Although GWAS analyses have reported that LRRFIP1 is associated with adiposity, inflammation, schizophrenia, and bipolar disorder in humans and lameness disorders in cattle, no studies have been reported in pigs." (PMID 39202462, 2024).
breast tumors (1 paper, 2012). "Notably, LRRFIP1 can be mutated in breast tumors and soft tissue sarcomas, and may be involved in the regulation of cell growth." (PMID 23181716, 2012).
Cerebral ischemia (1 paper, 2020). Restriction of arterial blood supply to the brain associated with insufficient oxygenation to support the metabolic requirements of the tissue. "Lrrfip1 is a brain protein upregulated in cerebral ischemia that activates β-catenin and regulates pro-survival pathways." (PMID 32300198, 2020).
corneal infection (1 paper, 2011). A viral or bacterial infectious process affecting the cornea. "However, that appears unlikely as corneal infection with vesicular stomatitis virus does not drive detectable pVEGFA-GFP reporter expression in reporter mice despite activation of MyD88- and TRIF-dependent TLRs as well as other pattern recognition receptors such as LRRFIP1 and RIG-I." (PMID 21998580, 2011).
epidermoid carcinoma (1 paper, 2019). "The epidermoid carcinoma cell lines with over-expressed LRRFIP1/GCF2 were reported to be sensitive to doxorubicin and vincristine, but resistant to cisplatin." (PMID 30709060, 2019). "One report, however, showed that over-expression of LRRFIP1/GCF2 repressed the expression of RhoA and disorganized the cytoskeletal system in an epidermoid carcinoma cell line." (PMID 30709060, 2019).
esophageal cancer (1 paper, 2022). A primary or metastatic malignant neoplasm involving the esophagus. "Another interesting point was the increase in the protein encoded by Lrrfip1, related to the presence of multinucleated giant cells, formed by fusion of circulating monocytes, involved in the phagocytosis of cancer cells and potentially associated with better survival in esophageal cancer patients." (PMID 36430209, 2022).
Hepatic steatosis (1 paper, 2015). Steatosis is a term used to denote lipid accumulation within hepatocytes. "Lrrfip1 expression was significantly associated with hepatic steatosis in our study (r = 0.56, p = 1.89 × 10−10)." (PMID 26067236, 2015).
inflammatory myofibroblastic tumor (1 paper, 2024). A multinodular intermediate fibroblastic neoplasm that arises from soft tissue or viscera, in children and young adults. "LRRFIP1 has been implicated in 8p11 myeloproliferative syndrome through its fusion with FGFR1, in inflammatory myofibroblastic tumors with ALK and in atypical Spitz tumors with MET." (PMID 38338888, 2024).
melanoma (1 paper, 2020). A malignant, usually aggressive tumor composed of atypical, neoplastic melanocytes. "Other tested DNA sensors (Cgas, Sting, Ddx41, Dhx9, Dhx36, Lrrfip1, Mre11, and additionally Aim2, which is absent in melanoma cells) were expressed in macrophages but were not significantly upregulated after irradiation." (PMID 33202881, 2020).
pneumonia (1 paper, 2024). An acute, acute and chronic, or chronic inflammation focally or diffusely affecting the lung parenchyma, caused by an infection in one or both of the lungs (by bacteria, viruses, fungi, or mycoplasma.). "LRRFIP1 (leucine-rich repeat flightless-interacting protein 1) was associated with the GW score in a severely affected farm and the SPES score in a mildly affected farm, and it could be a reliable genetic marker for improving pneumonia resistance in pigs." (PMID 39202462, 2024).
cancer (16 papers, 2012 to 2024). A tumor composed of atypical neoplastic, often pleomorphic cells that invade other tissues. "GSEA revealed that LRRFIP1 upregulation was significantly associated with various cancer-associated signaling pathways, including PI3K/AKT signaling pathway and Wnt pathway." (PMID 38634978, 2024). "Moreover, some researchers have confirmed that high LRRFIP1 expression is associated the cancer progression, including cancer cell proliferation, invasion, metastasis, and drug resistance." (PMID 38634978, 2024). "Several genes of considerable intrigue, such as LRRFIP1 and PTPN12, are repeatedly associated with transcription regulation and cancer-related pathways." (PMID 39684787, 2024). "LRRFIP1 acted important functions such as cell proliferation, distant metastasis, and invasion in the development of many malignant tumors." (PMID 35338570, 2022). "It, however, turned out that LRRFIP1/GCF2 worked rather advantageously for cancer by stimulating growth and inhibiting apoptosis." (PMID 30709060, 2019). "One gene stands out in the CR-APA group, LRRFIP1, as it has been shown to be overexpressed in cancer cell lines and to be pro-metastatic." (PMID 24782827, 2014). "We observed strong nuclear and weak cytoplasmic distribution of LRRFIP1 in cancer and normal cells except for MBC tumors, which showed moderate cytoplasmic staining in addition to strong nuclear staining." (PMID 23181716, 2012). "LRRFIP1 is abnormally expressed in a variety of cancers and regulates a wide range of biological systems and processes, including immune response to microorganisms and autoimmunity, remodeling of cytoskeletal system, signal transduction pathways, and transcriptional regulations of genes." (PMID 38634978, 2024). "Therefore, dysregulation of LRRFIP1 is critical in infections, autoimmune diseases, neurological, and cancers." (PMID 35338570, 2022). "In a recent publication from our group we demonstrated that the transcriptional co-repressor GCF2 (GC-Binding Factor 2) alias LRRFIP1 (Leucine Rich Repeat (In FLII) Interacting Protein 1) participates in TRIB3 downregulation in cancer cells incubated with rapamycin or its derivatives (rapalogs)." (PMID 33920424, 2021). "Another exception was that chemo-sensitivities to anti-cancer drugs, which accompanies growth effects, were affected with the level of LRRFIP1/GCF2 expression, in which some drugs worked in a way that inhibited growth in the presence of high LRRFIP1/GCF2 expression, while some induced resistance." (PMID 30709060, 2019). "LRRFIP1 has been reported in human and mouse with distinct roles in transcriptional repression, modulation of the innate immune response, regulation of cell division with an impact in cancer cells or wound healing, and as a modifier of platelet function and thrombosis." (PMID 33265962, 2020). "CR-APA of LRRFIP1 could thus also be a contributor to the tumorigenesis in SI-NETs, as the major mRNA isoform expressed in the SI-NETs is likely equal to that overexpressed in the cancer cell lines." (PMID 24782827, 2014). "It has been identified that LRRFIP1 plays a critical role in continuous growth, epithelial–mesenchymal transition (EMT), invasion, metastasis, and resistance to anti‐tumor drugs in cancers." (PMID 35338570, 2022). "In cancer, LRRFIP1/GCF2 plays important roles in the development of malignant phenotypes, such as continuous growth, epithelial-mesenchymal transition (EMT), invasion/metastasis, escape from apoptosis, susceptibility, and resistance to anti-cancer drugs." (PMID 30709060, 2019). "In accordance with our recent study, DIO1 expression resulted also in suppression of TGFBI, and several other proteins (e.g. PODXL, CD74) that promote RCC progression or act as oncogenic proteins in other cancers (e.g. FMNL2, APBB1IP, ASAP1, and LRRFIP1)." (PMID 29272308, 2017).
cancer (continued). "LRRFIP1 is a key regulator of EMT, and its repression inhibits migration and invasion in cancer cells, mediated by increased phosphorylation of β-catenin targeting it for destruction to reduce its nuclear localisation and decreasing the transcription of downstream EMT markers." (PMID 33330501, 2020). "LRRFIP-1 is a known modulator of the innate inflammatory responses including TLR signaling and cytokine secretion and has been shown to play an important role in cellular processes involved in cancer cell invasion." (PMID 29996558, 2018). "Targets of miR-21 in cancer include PTEN, PDCD4, LRRFIP1, RECK, TIMP-3, TPM1, BTG2, and Sprty2." (PMID 25366985, 2014).
tumor (16 papers, 2010 to 2024). "However, specific genes within the BRCA dataset such as H2AZ2 (H2A histone family member V) and LRRFIP1 (leucine-rich repeat flightless-interacting protein 1) exhibited a significant increase in TR in most tumor samples compared to normal tissues." (PMID 39349823, 2024). "LRRFIP1 plays an important role in the invasion of tumor cells." (PMID 36555319, 2022). "The miR-21 targets include the genespromoting apoptosis (PDCD4 and LRRFIP1), as well as the tumor suppressor genes inhibitinginvasion (RECK and TIMP3) and proliferation(IGFBP3).Furthermore, miR-21 can affect microglial behavior, thus ensuring favorableconditions for tumor growth." (PMID 34707896, 2021). "Because Wnt/β-catenin signaling is also linked to tumor development, further analyses may identify the machinery involved in the regulation of type I IFN signaling by Lrrfip1 under tumor development." (PMID 23316484, 2012). "EMT, which is a crucial mechanism that induces tumor metastasis and invasion, was stimulated by LRRFIP1/GCF2 through the Wnt/β-catenin pathway." (PMID 30709060, 2019). "The other tested DNA sensors (Rig-I, Cgas, Sting, Ddx41, Dhx9, Dhx36, Lrrfip1, Mre11) were expressed in the tumor cells but were not significantly upregulated after irradiation." (PMID 33202881, 2020). "As LRRFIP1/GCF2 was initially identified as a transcriptional repressor for several growth factors and their receptors, it was presumed that it played a role in inhibiting tumor growth." (PMID 30709060, 2019). "Common up-regulation of genes such as COL1A1, COL1A2, PGF, LRRFIP1, TMEFF2 or TGFB1 suggested an important role of this pool of cells in blood vessel formation, angiogenesis, permeability and proliferation pathways, essentials functions in tumour progression." (PMID 20735813, 2010).
infection (3 papers, 2013 to 2024). The state of being infected such as from the introduction of a foreign agent such as serum, vaccine, antigenic substance or organism. "This is in contrast to the LRRFIP1-dependent phosphorylation of CTNNB1 at Ser552 upon infection with Listeria monocytogenes, which promotes its transcriptional activation required for IFNB1 production in mouse macrophages." (PMID 23785285, 2013). "LRRFIP1 is a cytosolic nucleic acid-binding protein that recognizes both dsRNA and dsDNA and is known to produce IFN-β upon infection of the host with vesicular stomatitis virus and Listeria monocytogenes." (PMID 39202462, 2024). "While LRRFIP1 normally induces type I IFN expression in virally infected 3T3 cells, overexpression of LRRFIP1 can induce IFN expression regardless of infection status." (PMID 33330501, 2020).
infectious disease (2 papers, 2019 to 2024). A disorder directly resulting from the presence and activity of a microbial, viral, or parasitic agent in humans. "It is reasonable to speculate that dysfunction of LRRFIP1/GCF2 would lead to vulnerability to infectious disease." (PMID 30709060, 2019). "Previous studies reported that LRRFIP1 induces the production of type 1 interferon (IFN) and pro-inflammatory cytokines via binding nucleic acids in infectious diseases." (PMID 38634978, 2024).
cerebral artery (1 paper, 2019). "An isoform of rat LRRFIP1/GCF2 was significantly induced in an ischemic rat brain, especially in the peripheral area of infarction after middle cerebral artery occlusion." (PMID 30709060, 2019).
LRRFIP1 also shares sentences with these, for which no sentence is quoted: Anxiety (1 paper); Bacterial Infections (1); Cardiovascular Disease (1); cholangiocarcinoma (1); colon cancer (1); deep vein thrombosis (1); diabetes (1); fibrocystic disease (1); influenza (1); leukemia (1); malignant brain tumor (1); measles (1); medullary breast carcinoma (1); metabolic disease (1); mycoplasmal pneumonia (1); myocardial inflammation (1); Neurological Disorders (1); pancreatic ductal adenocarcinoma (1); rheumatoid arthritis (1); schizophrenia (1); soft tissue sarcoma (1).